GET4 (guided entry of tail-anchored proteins factor 4)
Description:
As part of a cytosolic protein quality control complex, the BAG6/BAT3 complex, maintains misfolded and hydrophobic patches-containing proteins in a soluble state and participates in their proper delivery to the endoplasmic reticulum or alternatively can promote their sorting to the proteasome where they undergo degradation. The BAG6/BAT3 complex is involved in the post-translational delivery of tail-anchored/type II transmembrane proteins to the endoplasmic reticulum membrane. Recruited to ribosomes, it interacts with the transmembrane region of newly synthesized tail-anchored proteins and together with SGTA and ASNA1 mediates their delivery to the endoplasmic reticulum. Client proteins that cannot be properly delivered to the endoplasmic reticulum are ubiquitinated and sorted to the proteasome. Similarly, the BAG6/BAT3 complex also functions as a sorting platform for proteins of the secretory pathway that are mislocalized to the cytosol either delivering them to the proteasome for degradation or to the endoplasmic reticulum. The BAG6/BAT3 complex also plays a role in the endoplasmic reticulum-associated degradation (ERAD), a quality control mechanism that eliminates unwanted proteins of the endoplasmic reticulum through their retrotranslocation to the cytosol and their targeting to the proteasome. It maintains these retrotranslocated proteins in an unfolded yet soluble state condition in the cytosol to ensure their proper delivery to the proteasome.
Synonyms: TRC35; C7orf20; CEE; CGI-20; H_NH1244M04.5; CDG2Y
Tractability: Small molecule: a structure with a bound ligand is known. PROTAC: UniProt records ubiquitination sites on it; ubiquitination databases record sites on it; its protein half-life has been measured.
Gene: Protein-coding gene on chromosome 7 (876,486 to 896,436, forward strand). Ensembl gene ENSG00000239857.
Subcellular location: Cytoplasm, cytosol
Subcellular location (Human Protein Atlas): Cytosol; Nucleoli; Mitotic chromosome; Nucleoplasm
Pathways (Reactome):
Protein localization: Insertion of tail-anchored proteins into the endoplasmic reticulum membrane
Gene Ontology:
Molecular function: protein binding; protein carrier chaperone; protein-folding chaperone binding
Biological process: ERAD pathway; post-translational protein targeting to endoplasmic reticulum membrane; protein insertion into ER membrane; regulation of protein stability; tail-anchored membrane protein insertion into ER membrane; ubiquitin-dependent protein catabolic process
Cellular component: BAT3 complex; cytoplasm; cytosol
Genetic constraint (gnomAD): Loss-of-function variants: 17 observed, 22.35 expected, observed/expected ratio (o/e) 0.76, 90% interval 0.52 to 1.14. The synonymous counts are far from expectation, so gnomAD's model fits this gene poorly and the ratio says little. Missense variants: 403 observed, 295.79 expected, observed/expected ratio (o/e) 1.36, 90% interval 1.25 to 1.48. Synonymous variants: 215 observed, 133.42 expected, observed/expected ratio (o/e) 1.61, 90% interval 1.44 to 1.8.
Homologues: Orthologues: chimpanzee GET4 (99% identical), macaque GET4 (96% identical), mouse Get4 (95% identical), dog GET4 (95% identical), guinea pig GET4 (94% identical), tropical clawed frog get4 (87% identical), zebrafish get4 (84% identical), Drosophila melanogaster CG9853 (37% identical), Caenorhabditis elegans cee-1 (27% identical).
Diseases named in the same sentence as GET4 in open-access papers:
GET4 is named in the same sentence as 18 diseases in open-access papers, as found by Europe PMC text mining. Sharing a sentence is not in itself a finding about the gene and the disease. The quoted sentences say what the papers report.
colorectal cancer (3 papers, 2021 to 2023). A primary or metastatic malignant neoplasm that affects the colon or rectum. "Furthermore, a study in colorectal cancer reported that Golgi to ER traffic protein 6 (Get4) has been considered to promote tumorigenesis or tumor progression by demonstrating clinical significance of Get4 expression in colorectal cancer." (PMID 33947955, 2021). "KCTD5 has been identified as having a role in cell migration 28, 29; and GET4, as part of a larger protein complex with BAG6, has been shown to play a role in the recruitment of BRCA1 to sites of DNA damage 30 and promote tumour growth in models of colorectal cancer." (PMID 37771787, 2023).
type 1 diabetes (2 papers, 2023 to 2025). "GET4 and JKAMP have recently been identified as valuable biomarkers in diabetic cardiomyopathy in type 1 diabetes." (PMID 41465472, 2025).
Alzheimer disease (1 paper, 2024). A progressive, neurodegenerative disease characterized by loss of function and death of nerve cells in several areas of the brain leading to loss of cognitive function such as memory and language. "Finally, we show that loss of GET4 rescues motor ability, improves lifespan and prevents neurodegeneration in a Drosophila model of Alzheimer’s disease (Aβ42Arc)." (PMID 38467609, 2024).
congenital myasthenic syndrome (1 paper, 2023). Congenital myasthenic syndrome (CMS) is a group of genetic disorders of impaired neuromuscular transmission at the motor endplate characterized by fatigable muscle weakness. "Some examples of other (including multiple) glycosylation pathway defects discovered in the last five years are ATP6VI1-, GO7- (Congenital myasthenic syndrome), GET4-, GFUS- and GNPNAT1-CDG, and most recently CAMLG-CDG." (PMID 37858231, 2023).
mammary tumors (1 paper, 2021). "To further verify the identified target genes that showed significant changes in DE and DM patterns in response to the combination treatment, we evaluated the expression of Pdx1, Tmem132d, Get4, Rpl13 and Ndufa1 genes in mouse mammary tumors using qRT-PCR." (PMID 33947955, 2021).
metastatic tumor (1 paper, 2021). "In addition, we explored the roles of CRB3 and GET4 in pancancer screening on the "Data explorer" module of the DepMap database, including RCC and non-RCC, MSI and MSS, and primary and metastatic tumor cell lines." (PMID 33850477, 2021).
oral cancers (1 paper, 2022). "Transcriptome analysis suggested that miRNA-1307-5p could promote oral cancer progression by suppressing THOP1, EHF, RNF4, GET4 and RNF114." (PMID 36142544, 2022). "Interestingly, to the best of our knowledge, apart from EHF, no studies have reported the association of THOP1, RNF4, GET4 and RNF114 with oral cancers." (PMID 36142544, 2022).
tumor (7 papers, 2015 to 2026). "Epigenome-wide association analysis identified clusters of CpGs on chromosomes 6 and 7, mapping to genes such as KIF13A and GET4, reinforcing the concept that methylation changes in cytoskeleton- and transport-related genes could contribute to tumor progression." (PMID 41597272, 2026). "Furthermore, CRB3 seemed to be a potential broad tumor suppressor gene, while GET4 might be a ccRCC preferential dependency gene with a ligandable structure that could facilitate future drug development." (PMID 33850477, 2021). "Bioinformatics analysis revealed that miR-1307-5p likely contributes to cancer progression by downregulating tumor-suppressive genes, such as THOP1, EHF, RNF4, GET4, and RNF114." (PMID 40699851, 2025). "Bioinformatics analysis suggested that miR-1307-5p promotes cancer progression by suppressing key tumor suppressor genes such as THOP1, EHF, RNF4, GET4, and RNF114." (PMID 40699851, 2025). "B4GALT4, BCL2L1, COPG1, CRB3, GET4, and TFRC showed almost the same expression levels between tumor and normal tissues." (PMID 33850477, 2021). "In the univariable Cox analysis, clinical tumor stage, age, and the expression levels of NFE2L2, ITGAV, GET4, FERMT2, CRB3, CDH2, and BCL2L1 were prognostic factors for OS." (PMID 33850477, 2021). "Based on the multivariable Cox models, GET4 and CRB3 were independent prognostic factors after adjusting for tumor stage and patient age and sex." (PMID 33850477, 2021). "Compared to that in non-RCC cell lines, GET4 had a preferential role as a tumor dependency gene in RCC, and it seemed that microsatellite instability or tumor type did not affect the functions of GET4 across the cell lines." (PMID 33850477, 2021).
cancer (3 papers, 2020 to 2025). A tumor composed of atypical neoplastic, often pleomorphic cells that invade other tissues. "In contrast, GET4 (Golgi to ER traffic protein 4 homolog) showed preferential ccRCC dependency among different lineages of cell lines, and the correlation between GET4 and cancer has been poorly studied." (PMID 33850477, 2021).
GET4 also shares sentences with these, for which no sentence is quoted: common variable immunodeficiency (1 paper); congenital disorder of glycosylation (1); diabetic cardiomyopathy (1); gastrointestinal disease (1); motor neuron disease (1); neutropenia (1); polycystic liver disease (1); schizophrenia (1); tubulointerstitial kidney disease (1).